CREB3L1 (cAMP responsive element binding protein 3 like 1)
Diseases named in the same sentence as CREB3L1 in open-access papers (continued):
Sharing a sentence is not in itself a finding about the gene and the disease.
breast carcinoma (continued). "Breast cancer cell lines and tumor samples were analyzed similarly, and CREB3L1 gene methylation was determined using sodium bisulfite conversion and DNA sequencing." (PMID 26810754, 2016). "Large breast cancer database analyses were carried out to examine relationships between CREB3L1 gene methylation and mRNA expression in addition to CREB3L1 mRNA expression and prognosis." (PMID 26810754, 2016). "Our breast cancer cell line data suggested that CREB3L1 expression can be regulated in part by DNA methylation." (PMID 26810754, 2016). "When all breast cancers were analyzed as a group there was a shorter relapse-ree survival time for patients whose tumors contained low levels of CREB3L1 mRNA expression (hazard ratio (HR) = 1.27; p <0.0001)." (PMID 26810754, 2016). "We also compared the distribution of breast cancer subtypes by their nuclear and cytoplasmic localization and levels of CREB3L1 protein expression." (PMID 26810754, 2016). "Tumors in TNBC are known to have hypermethylated DNA and consistent with this, we see enhanced methylation of several key CpG sites within the CREB3L1 gene that strongly correlate with reduced expression in breast cancer cell lines and in human breast tumors." (PMID 26810754, 2016). "Luminal breast cancers were more frequently observed to have low-medium levels of CREB3L1, effectively localized to the nucleus, or high levels of CREB3L1 within the cytoplasm." (PMID 26810754, 2016). "Quantitative real time PCR (qPCR) and immunoblotting were used to determine the impact of histone deacetylation and DNA methylation inhibitors on CREB3L1 expression in breast cancer cell lines." (PMID 26810754, 2016). "Our previous work showed that highly metastatic rat and human breast cancer cell lines had reduced expression of CREB3L1 compared to poorly metastatic breast cancer cell lines." (PMID 26810754, 2016). "CREB3L1 plays a tumor-suppressive role in breast cancer: prolonged CREB3L1 expression under cytotoxic conditions induces apoptosis as opposed to favoring tumor cell survival and has been found to negatively regulate various oncogenes that enhance breast cancer development." (PMID 40427627, 2025). "The phenotypes of some of the CREB3L1-deficient parental breast cancer cell lines were altered by the expression of HA-CREB3L1, although the cell doubling times were not significantly impacted." (PMID 35802566, 2022). "CREB3L1 (cAMP-responsive element binding protein 3 like 1) is a metastasis suppressor that functions as a transcription factor, and in an estrogen-dependent model of rat breast cancer, it repressed the expression of genes that promote breast cancer progression and metastasis." (PMID 35802566, 2022). "Therefore, we selected four CREB3L1-deficient breast cancer cell lines for functional analysis, two basal TNBC cell lines (HCC1806 and HCC70) and two luminal A breast cancer cell lines (HCC1428 and T47D)." (PMID 35802566, 2022). "In this report, we set out to determine the expression level of CREB3L1 across different human breast cancer subtypes and determine whether CREB3L1 functions as a metastasis suppressor, particularly in triple negative breast cancers (TNBCs)." (PMID 35802566, 2022). "Besides, cancer-specific PERK signaling induces cell invasion and metastasis through directly targeting CREB3L1 in breast cancer through inducing epithelial-mesenchymal transition (EMT) by an ATF4-Fra-1 interaction." (PMID 36171879, 2022). "In rat breast cancer cells, chromatin immunoprecipitation and microarray analysis demonstrated that CREB3L1 negatively regulates genes that contribute to cell migration, invasion, angiogenesis and metastasis and positively regulates genes involved in tumor suppression." (PMID 35802566, 2022). "CREB3L1 is not typically mutated in cancers, but CREB3L1 functions as a metastasis suppressor in breast cancer and bladder cancer." (PMID 35802566, 2022).
breast carcinoma (continued). "Furthermore, knockdown of CREB3L1 mRNA in human hepatoma Huh7 cells conferred increased resistance to DOX, whereas overexpression of CREB3L1 in human breast cancer MCF-7 cells markedly enhanced DOX sensitivity in these cells." (PMID 34632049, 2021). "In the mesenchymal subtype of TNBC, PERK signaling enhanced invasion and metastasis through interaction with the transcription factor CREB3L1 (cAMP responsive element binding protein 3 like 1), and its knockdown inhibited growth of breast carcinoma in animal models by limiting redox homeostasis." (PMID 32039198, 2019). "Moreover, recent study indicated that CREB3L1 was a key downstream mediator of PERK-driven metastasis in breast cancer." (PMID 31183379, 2019). "Since the mechanism through which CREB3L1 is activated can be effectively targeted by small-molecule inhibitors, our findings suggest a promising new therapeutic strategy for this clinically important subtype of breast cancer." (PMID 29057869, 2017). "To explore these additional pathways, we segregated breast cancers that have active PERK signaling into two categories according to the expression level of CREB3L1 (CREB3L1-high and CREB3L1-low, respectively), and employed gene set enrichment analysis (GSEA) to compare these two cohorts." (PMID 29057869, 2017). "Although these cancer types (including breast cancer) typically show an increase in CREB3L1 expression, patients with tumors expressing low levels of CREB3L1 may experience a poorer prognosis, as we found for breast cancer." (PMID 26810754, 2016). "Further, in luminal breast cancers, again about half express CREB3L1, that in lower grade tumors is typically nuclear, where it could regulate transcriptional targets, and in higher grade tumors is typically cytoplasmic, where it could not." (PMID 26810754, 2016). "In contrast, HER2 amplified breast cancers contained mainly high levels of cytoplasmic CREB3L1." (PMID 26810754, 2016). "Further the high CREB3L1 mRNA levels and low protein expression observed in some breast cancer cell lines (e.g., HCC202) could be the result of translational deregulation or the rapid turnover of CREB3L1 protein." (PMID 26810754, 2016). "We analyzed the methylation status of the CREB3L1 promoter region, as one possible mechanism that could regulate CREB3L1 expression in breast cancer cells." (PMID 26810754, 2016). "Our data in human breast cancer cell lines suggest that epigenetic silencing of CREB3L1 contributes to reducing CREB3L1 mRNA expression for at least some cell lines, an effect that was reversed by the inhibition of histone acetylation with TSA and/or inhibition of DNA methylation with DAC." (PMID 26810754, 2016). "Moreover, in an in vivo rat mammary tumor model, CREB3L1-expressing cells fail to develop metastases and experience impaired angiogenesis relative to CREB3L1-null cells, indicating its important role in suppressing tumorigenesis." (PMID 27121396, 2016). "Thus, drug sensitivity may be impacted differently by CREB3L1 expression in different breast cancer cell lines, or in different breast cancer subtypes." (PMID 36123435, 2022). "Since luminal A breast cancers that are CREB3L1-deficient also show a poor prognosis as compared to those expressing CREB3L112, we extended this analysis to determine the drug sensitivity in several luminal A breast cancer cell lines, some of which were also tested with re-expressed CREB3L1." (PMID 36123435, 2022). "The assays confirmed that CREB3L1, CAPG, and SPINT1 were significantly upregulated in breast cancer group, while GRK3 was significantly downregulated when compared to normal group, respectively." (PMID 39015775, 2024). "Pathologically, CREB3L1 implicates in the modulation of osteogenesis imperfecta, low grade fibro myxoid sarcoma (LGFMS), sclerosing epithelioid fibrosarcoma (SEF), glioma, breast cancer, thyroid cancer, and tissue fibrosis." (PMID 38164349, 2024).
breast carcinoma (continued). "CREB3L1 acts as the downstream signal of PERK to regulate the expression of collagen I and FN1 and promote the invasion and metastasis of breast cancer." (PMID 36192735, 2022). "Restoration of CREB3L1 expression in HCC1806 cells was also sufficient to reduce mammary fat pad tumor formation and lung metastases in mouse xenograft models of breast cancer as compared to the parental HCC1806 cells." (PMID 35802566, 2022). "CREB3L1 expression was generally increased in luminal A, luminal B and HER2 breast cancers, but significantly reduced in a high proportion (75%) of TNBCs." (PMID 35802566, 2022). "Though the mechanism(s) for lack of CREB3L1 gene expression is not clear in tumor progression, methylation of the gene could be a cause involved in negatively regulating CREB3L1 mRNA expression in breast cancer cells." (PMID 29531016, 2018). "We found that more than half the breast cancer cell lines contained CREB3L1 methylated CpG sites; in particular, those of the TNBC subtype of breast cancer were highly methylated." (PMID 26810754, 2016). "Similar to what we had observed for our smaller tumor dataset, CREB3L1 mRNA expression was increased in luminal and HER2 breast cancers but was low in TNBC." (PMID 26810754, 2016). "BT20, HCC1806 and MDA-MB-468 human breast cancer cells were treated with DAC and/or TSA and CREB3L1 mRNA levels were analyzed by qPCR, relative to a GAPDH-specific control." (PMID 26810754, 2016). "CREB3L1, CAPG, SPINT1, and GRK3 might be suitable for clinical application in early breast cancer treatment." (PMID 39015775, 2024). "This suggests that cell cycle progression and cell proliferation functions are not greatly impacted by CREB3L1 expression in breast cancer cells." (PMID 35802566, 2022). "Upon ER stress, CREB3L1 (cyclic AMP (cAMP)-responsive element-binding protein 3-like protein 1), a member of UPR, plays an opposite role on the angiogenesis of highly metastatic breast cancer cells (LN4D6) and its angiogenesis." (PMID 31121863, 2019). "Although not specific to breast cancer, CREB3L1, like the other members of the UPR, has also been shown to perform important roles in cancer." (PMID 26810754, 2016). "When breast cancers were subdivided into different molecular classifications, CREB3L1 mRNA expression did not significantly influence the relapse-free survival time for luminal B (ER+ and/or PR+, HER+ or HER2– with high Ki67) and HER2 breast cancer patients." (PMID 26810754, 2016). "As similar results were not seen for luminal B and HER2 amplified breast cancers, the impact of low CREB3L1 expression may not be significant in the context of HER2 expression." (PMID 26810754, 2016). "However, as we saw for breast cancers with reduced CREB3L1, like TNBC, the disease is typically more aggressive and advanced resulting in a poor prognosis within these groups if tumors have reduced CREB3L1." (PMID 26810754, 2016). "In this report, we characterize the expression of CREB3L1 in a large panel of breast cancer and non-cancer cell lines and determine whether epigenetic mechanisms regulate CREB3L1 expression in breast cancer." (PMID 26810754, 2016). "In contrast, the survival of breast cancer patients with tumors that express amplified HER2 (HER2 and luminal B) do not appear to be significantly influenced by alterations in CREB3L1 expression." (PMID 35802566, 2022). "In contrast, breast cancers that express amplified levels HER2 (i.e. luminal B and HER2) do not appear to be impacted positively or negatively by CREB3L1 expression levels." (PMID 35802566, 2022). "In conclusion, we have demonstrated that CREB3L1 is frequently upregulated in luminal and HER2 amplified breast cancer, but not in TNBC." (PMID 26810754, 2016).
osteogenesis imperfecta (14 papers, 2013 to 2025). Osteogenesis imperfecta (OI) comprises a heterogeneous group of genetic disorders characterized by increased bone fragility, low bone mass, and susceptibility to bone fractures with variable severity. "In a clinical study of osteogenesis imperfecta in cat, the CREB3L1 mutation was found to cause severe osteogenesis imperfecta." (PMID 35563641, 2022). "Moreover, ustekinumab treatment significantly increased mRNA expression of CREB3L1 gene encoding a transcription factor involved in bone formation; CREB3L1 deficiency can cause severe osteogenesis imperfecta." (PMID 33746955, 2021). "Aside from the pathogenic variants in COL1A1, COL1A2 and CREB3L1, we were unable to identify any other mutual variant related to collagen type I that could explain the phenotype with osteogenesis imperfecta and oligodontia." (PMID 32234057, 2020). "In humans, homozygous genomic deletion of CREB3L1, which encodes OASIS, was detected in Turkish patients with severe osteogenesis imperfecta, which is a heterogenous congenital disorder characterized by increased bone fragility." (PMID 28208663, 2017). "In addition, somatic mutations in CREB3L1 contribute to osteogenesis imperfecta (OI), while the generation of Fused in sarcoma (FUS)-CREB3L1 and EWS RNA Binding Protein 1 (EWSR1)-CREB3L1 lead to LGFMS and sclerosing epithelioid fibrosarcoma (SEF) respectively." (PMID 38164349, 2024). "Notably, our enrichment analysis includes CREB3L1 and COL1A1, which, out of the top 10 genes, are associated with osteogenesis imperfecta type III (disorder)." (PMID 37508851, 2023).
glioma (10 papers, 2011 to 2024). A benign or malignant brain and spinal cord tumor that arises from glial cells (astrocytes, oligodendrocytes, ependymal cells). "CREB3L1 is expressed in the brain but is also a prominent transcription factor in cancer biology that has been studied as a biomarker in glioma, given its association with tumor grade and survival." (PMID 39123468, 2024). "Knockdown of CREB3L1 in glioma cells resulted in decreased expression of extracellular matrix proteins and attenuated ER stress response." (PMID 31183379, 2019). "The CREB3L1 mRNA level in the brain specimens displayed a gradient decrease with an increase in the PTN mRNA level from the control to high-grade glioma tissues." (PMID 29531016, 2018). "In contrast with the control all with CREB3L1+, a proportion for the CREB3L1-presenting population gradually reduced to 76 and 40% in the survivors with the low- and high-grade gliomas." (PMID 29531016, 2018). "In contrast with the control, the population proportion for the CREB3L1+ staining was reduced to 76 and 40% in the patients with low- and high-grade gliomas (n=17 and 25), respectively." (PMID 29531016, 2018). "A relative level for the CREB3L1 mRNA expression was displayed as 2.59 (1.48) in the control cells, 1.30 (0.89) and 0.34 (0.75) in the low- and high-grade glioma cells, respectively." (PMID 29531016, 2018). "The decrease in the CREB3L1 mRNA expression was associated with the increase in the PTN mRNA expression in the low- and high-grade gliomas (P<0.05)." (PMID 29531016, 2018). "The CREB3L1 mRNA expression levels in the low- and high-grade glioma cells were 1.99- and 7.59-fold lower than the control." (PMID 29531016, 2018). "An E3 ubiquitin ligase, HRD1, has been reported to ubiquitinate CREB3L1 to induce proteasomal-mediated degradation in C6 glioma cells and mouse embryonic fibroblasts to maintain low levels of CREB3L1 protein." (PMID 26810754, 2016). "In the present study, the numbers of CREB3L1+ cells in the same microscope’s field of view gradually decreased from the control to the high-grade glioma, whereas the PTN+ cell counts increased in the low- and high-grade glioma tissues as compared with the control." (PMID 29531016, 2018). "CREB3L1+ cell counts were reduced from the normal as compared with the high-grade glioma tissues." (PMID 29531016, 2018). "Since these changes of the glioma tumors at the gene level were identical with the results observed at their protein levels, it is reasonable to consider that CREB3L1 and PTN serve as biomarkers for helping to identify the nature of the glial cells and evaluating malignant degrees of brain gliomas." (PMID 29531016, 2018). "As CREB3L1 protein levels have been reported to be downregulated via constitutive ubiquitination and proteasomal degradation in mouse embryo fibroblasts and C6 glioma cells, the TSA and/or DAC treatments were repeated including the proteasomal inhibitor, MG132." (PMID 26810754, 2016). "Moreover, previous study in C6 glioma cells showed that ER stress inducer dithiothreitol can activate CREB3L1 at the protein level, while the mRNA level is unchanged." (PMID 26503226, 2015). "Both CREB3L1 and CREB3L2 were previously implicated in UPR in astrocytes or glioma cells." (PMID 21711675, 2011). "Population distribution for the CREB3L1- and PTN-presenting patients was examined in patients with low- and high-grade gliomas, as well as a control group." (PMID 29531016, 2018). "CREB3L1 and PTN mRNA expression was measured in the brain specimens obtained from the control glial cells, low- and high-grade glioma cells." (PMID 29531016, 2018). "CREB3L1+ cell counts were decreased with increased PTN+ cells in the low-grade and high-grade glioma tissues as compared with the control." (PMID 29531016, 2018). "Survival time for patients with CREB3L1− and PTN+ gliomas was shorter than patients with CREB3L1+ and PTN− gliomas in the investigated cohorts (both P<0.05)." (PMID 29531016, 2018).
glioma (continued). "Based on our data and these reports, it is conceivable that the changes in the CREB3L1 and PTN expression levels were related to the aggressive behaviors (invasion and metastasis) of the glioma cells in disease progression." (PMID 29531016, 2018). "ER stress has been at the forefront of investigations surrounding regulation of Creb3l1 synthesis and cleavage by RIP since this mechanism was first identified in C6 glioma cells." (PMID 29311806, 2017). "Population proportion of the CREB3L1+-presenting patients decreased from the control to the high-grade glioma and the population of the PTN+-presenting patients increased in low- and high-grade gliomas as compared with the control (both P<0.05)." (PMID 29531016, 2018). "Furthermore, changes in the CREB3L1 and PTN expression levels in the tumor cells offer the potential to assess prognosis of the glioma patients." (PMID 29531016, 2018). "CREB3L1 and PTN expression levels serve as biomarkers with utility in grading gliomas." (PMID 29531016, 2018). "CREB3L1 and PTN expressions have been involved in human gliomas." (PMID 29531016, 2018). "In C6 glioma cells and cultured astrocytes, early studies showed that Creb3l1 was involved in the unfolded protein response (UPR), identifying ER chaperone protein 78-kDa glucose-regulated protein (Grp78) as a target of Creb3l1 effects." (PMID 29311806, 2017). "Absence of CREB3L1 and presence of PTN in brain glioma cells correlate with survival time of the glioma patients." (PMID 29531016, 2018). "Absence of CREB3L1 and presence of PTN expression in the tumor cells correlate with a poor prognosis of the glioma patients." (PMID 29531016, 2018).